MAPK3 (mitogen-activated protein kinase 3)
Diseases named in the same sentence as MAPK3 in open-access papers (continued):
Sharing a sentence is not in itself a finding about the gene and the disease.
lung adenocarcinoma (71 papers, 2011 to 2025). A carcinoma that arises from the lung and is characterized by the presence of malignant glandular epithelial cells. "The five largest node targets identified were protein kinase 1 (AKT1), STAT3, JUN, interleukin-6 (IL-6), and mitogen-activated protein kinase 3 (MAPK3), which may be important targets for the treatment of lung adenocarcinoma with QSFZYL." (PMID 40642092, 2025). "MOV10, encoding Mov10 RISC complex RNA helicase, was reported to be highly expressed with POLR2A, MAPK3, and XAB2 in 95% of 54 lung adenocarcinoma (LUAD) cases with poor prognosis." (PMID 34616428, 2021). "The K‐M plotter database indicated that high expression of POLR2A, MAPK3, MOV10, and XAB2 predicted poor prognosis in lung adenocarcinoma." (PMID 33001583, 2020). "High expression of POLR2A, MAPK3, MOV10, and XAB2 predicted poor prognosis in lung adenocarcinoma, as verified by the K‐M plotter database." (PMID 33001583, 2020).
depression (69 papers, 2012 to 2026). "Blood samples from patients with depressive disorders were analyzed for MAPK3 expression, and a mouse model of CO-induced depression was employed to further explore the molecular mechanisms." (PMID 40370374, 2025). "Blood levels of MAPK3 mRNA in patients with depression (i.e., Case) were found significantly elevated by nearly 2 folds compared to those in healthy individuals (i.e., Control) (p < 0.05)." (PMID 40370374, 2025). "This study also presented data to further support the important functional role of MAPK3 and its signaling pathway in CO-induced depression and mental disorders." (PMID 40370374, 2025). "The transcript levels of MAPK3 in the blood samples of patients with depressive disorder were also found significantly elevated compared to healthy individuals." (PMID 40370374, 2025). "MAPK3 transcript was found elevated in blood samples of patients with depression, while suppressing MAPK3 activity with an inhibitor could alleviate adverse effects in mouse model of CO-induced depression." (PMID 40370374, 2025). "Inhibition of MAPK3 could alleviate the adverse effect of CO-induced depressive disorder in mice, strengthening the notion that MAPK3 and its associated signaling would be essential to mental disorders associated with CO pollution." (PMID 40370374, 2025). "Additionally, elevated MAPK3 expression was found in the blood samples of depressed patients, and treatment with the MAPK inhibitor PD98059 alleviated CO-induced depression in a mouse model." (PMID 40370374, 2025). "PPI network analysis identified core targets such as MAPK3, STAT3, AKT1, PRKACA, MAPK1, and TNF, suggesting BCBL's efficacy in depression treatment may stem from its action on multiple key targets." (PMID 40909251, 2025). "Many of these genes have been previously linked to brain-related disorders, including Alzheimer’s disease (WDR12, AGFG2, and CDK5RAP3), schizophrenia (SRA1, WDR55, CORO7, DDAH2, PCDHA8), autism spectrum disorder (MAPK3, PCDHA13), and major depressive disorder (ZMAT2 and ITIH4)." (PMID 39269986, 2024). "The interaction pathway between CLM and depression is mainly enriched in PI3K-Akt, JAK-STAT, and NF-κB signaling pathway, PIK3R1, MAPK3, and AKT1 may be the potential targets of Stigmasterol, β-stiosterol, coumestrol." (PMID 37808199, 2023).
liver cancer (69 papers, 2014 to 2025). An epithelial or non-epithelial malignant neoplasm that arises from the liver. "It is important to note that two of our major targets, MTOR and MAPK3, are primarily implicated in liver cancer resistance pathways." (PMID 35745580, 2022). "This gives clear evidence that dysregulation of the MAPK3 gene causes disturbance in the MAPK signaling pathway, which ultimately leads to liver cancer." (PMID 35745580, 2022). "We found that the expression of MAPK3 in liver cancer tissue is higher than that in normal tissue by immunohistochemical staining in the HPA database." (PMID 35938001, 2022). "There is a strong correlation between MAPK3 and liver cancer resistance." (PMID 36817123, 2023). "Therefore, by targeting MAPK3, the pathophysiology of liver cancer can be halted." (PMID 35745580, 2022). "Compared to normal liver tissue, the mRNA levels of XRCC1, MAPK3, and PCNA were significantly elevated in liver cancer tissue." (PMID 39346898, 2024). "The results of molecular docking predicted that several key targets of liver cancer (along with MTOR, EGFR, MAPK3, and PIK3R1) bind stably with the corresponding active ingredient of F. indica." (PMID 35745580, 2022). "Comparing these findings with those provided by enrichment analysis four genes in particular, EGFR, MAPK3, MTOR, and PIK3R1, were identified as the main anti-liver cancer targets of F. indica and were chosen for molecular docking experiments." (PMID 35745580, 2022). "Wu found through network pharmacological analysis that the YQJPJD formula mainly regulates potential therapeutic targets of liver cancer through key ingredients such as luteolin, quercetin and baicalin and exerts anti-liver cancer effects through core targets such as RAC1, MAPK3, and RHOA." (PMID 39806972, 2025). "Furthermore, our studies revealed that the EGFR, MAPK3, MTOR, and PIK3R1 genes are effective and potential therapeutic agents for lowering the incidence of liver cancer and potentially exhibiting therapeutic effects on liver cancer." (PMID 35745580, 2022). "Furthermore, we analyzed the active ingredient-target-pathway network and uncovered that Fumaridine, Lastourvilline, N-feruloyl tyramine, and Cryptopine conclusively contributed to the development of liver cancer by affecting the MTOR, MAPK3, PIK3R1, and EGFR gene." (PMID 35745580, 2022).
Cerebral ischemia (61 papers, 2010 to 2025). Restriction of arterial blood supply to the brain associated with insufficient oxygenation to support the metabolic requirements of the tissue. "Accumulating evidence has confirmed that, under the injuries of stroke, cerebral ischemia, and I/R and activation of PI3K/Akt or PI3K/Akt/mTOR signaling pathway, PIK3CA, PIK3R1, AKT1, MAPK1, MAPK3 are main genes that play important roles in promoting cell survival and reducing cellular apoptosis." (PMID 35432563, 2022).
heart failure (61 papers, 2009 to 2026). Inability of the heart to pump blood at an adequate rate to meet tissue metabolic requirements. "Mice engineered to express Ptpn11Q79R in the fetal cardiomyocytes develop ventricular septal defects and heart failure in an ERK1/2 (also known as MAPK3/1)-dependent manner." (PMID 35178568, 2022). "However, over-activated MAPK3 can lead to dilated cardiomyopathy and heart failure." (PMID 35145551, 2022). "Findings from GWAS and Mendelian randomization-proteomics identify seven (CAMK2D, PRKD1, PRKD3, MAPK3, TNFSF12, APOC3 and NAE1) proteins as potential targets for interventions to be used in primary prevention of heart failure." (PMID 37429843, 2023).
asthma (56 papers, 2006 to 2026). "Protein encoded by MAPK3 was found to have an indirect effect on asthma mediated by FEV1/FVC." (PMID 40136421, 2025). "Subsequently, with these proteins related to pulmonary diseases, we found three potential mediation pathways including indirect effect of EFEMP1 on COPD via FEV1/FVC, an indirect effect of MAPK3 on Asthma via FEV1/FVC and an indirect effect of NPNT on COPD risk via FEV1/FVC." (PMID 40136421, 2025). "Thus, MAPK3-encoded protein may improve lung function and, in turn, ameliorate asthma." (PMID 40136421, 2025). "As TGFRB1, FOXO3, and PTEN are target genes of hsa-miR-148b-3p, and MAPK3 is the objective gene of hsa-miR-221-5p, all are involved in the signaling pathways related to asthma disease." (PMID 36675122, 2023). "In QFXY-asthma target network, Hsp90α, Mapk3, VIM were hub proteins suggesting that they may be some targets of QFXY pills." (PMID 23919426, 2013). "PWAS identified IL6R, MAPK3, and CSF2 as the proteins most extensively shared between glycemic traits and asthma." (PMID 41300562, 2025). "In our study, we employed a network pharmacology approach to prioritize seven predicted targets (AKT1, VEGFA, EGFR, SRC, MAPK3, MMP9, MAPK1) of baicalein for asthma treatment, and confirmed its high binding affinity to these targets through molecular docking." (PMID 38178132, 2024). "Expression of hsa-miR-148b-3p and hsa-miR-221-5p correlated with FEV1/FVC (%) and these altered miRNAs act in key signaling pathways for asthma disease and the regulated expression of some genes (FOXO3, PTEN, and MAPK3) involved in these pathways." (PMID 36675122, 2023). "In this study, the IL-17 signaling pathway was found by the KEGG enrichment analysis to be an important pathway by which the PEF counteracted asthma, and 15 targets are involved (including the core targets MAPK1, MAPK14, MAPK3, and JUN)." (PMID 36172200, 2022). "Among these proteins, MAPK3, IL6R, and CSF2—the most widely shared proteins—emerged as potential key regulators influencing the comorbidity of glucose metabolism dysregulation and asthma." (PMID 41300562, 2025). "Finally, we obtained 7 predicted targets of baicalein for asthma treatment, namely AKT1, VEGFA, EGFR, SRC, MAPK3, MMP9, MAPK1." (PMID 38178132, 2024). "Further validation by reverse transcription quantitative polymerase chain reaction (RT-qPCR) and western blotting analysis revealed that the VEGF and EGFR signaling pathways involving VEGFA, MAPK1, MAPK3, and EGFR were inhibited by baicalein in the asthma mouse model." (PMID 38178132, 2024). "A total of 129 overlapping targets between the PEF and asthma were obtained by jvenn online tools, among which five targets might play important roles: MAPK14, JUN, STAT3, MAPK3, and MAPK1." (PMID 36172200, 2022).
Hypertension (52 papers, 2010 to 2025). The presence of chronic increased pressure in the systemic arterial system. "The results indicate that in the Ang II-induced hypertension group, the expression levels of TNF, NFKB1, MAPK3, PTGS2, and RELA were markedly elevated compared to the control group, while the expression levels of HSP90AA1, HSP90AB1, PPARG, SIRT1, MAPK1, and PRKCA were significantly decreased." (PMID 39592923, 2024).
viral infection (52 papers, 2007 to 2025). "MAPK1, MAPK3, MAPK8 and MAPK14 can be activated by stimulating phosphorylation during changes in the internal environment, such as osmotic pressure changes, oxidative stress, inflammatory factors and viral infection." (PMID 35165507, 2022).
liver fibrosis (51 papers, 2014 to 2025). "Therefore, Hugan tablets may inhibit the activation of the PI3K-Akt signaling pathway through IL-6, AKT1, VEGFA, EGFR, and MAPK3, thereby inhibiting the activation of HSCs and delaying the occurrence of liver fibrosis." (PMID 34262454, 2021). "Moreover, miR-122 also plays an important role in the study of liver fibrosis, and reducing its expression may induce downregulation of some liver reconstitution regulators such as mitogen-activated protein kinase 3, which could reflect the extent of liver regeneration under pathological conditions." (PMID 37223047, 2023).
Sepsis (50 papers, 2011 to 2025). Sepsis is defined as life-threatening organ dysfunction caused by a dysregulated host response to infection. "These genes with high degrees in the PPI network have been reported to participate in some signaling pathways associated with sepsis, such as the cytokine–cytokine receptor interaction (hsa04060), NF-κB signaling pathway, and MAPK3 signaling pathway." (PMID 34938184, 2021). "The area under the receiver operating characteristic curve (AUROC) for diagnosing sepsis using MAPK3 was found to be 0.850 (95% CI 0.639–1.000), demonstrating a sensitivity of 0.800 and a specificity of 1.000." (PMID 40070882, 2025). "Through bioinformatics analysis, we identified five genes associated with ferroptosis—MAPK3, MAPK8, PPARG, PTEN, and STAT3—that may contribute to sepsis-related tissue damage." (PMID 40070882, 2025). "In conclusion, our study successfully identified MAPK3, MAPK8, PPARG, PTEN, and STAT3 as potential ferroptosis-related genes involved in the progression of sepsis." (PMID 40070882, 2025). "MAPK3, PTEN, and STAT3 were significantly upregulated in pediatric sepsis, consistent with the results of GSE145227." (PMID 40070882, 2025). "The AUROCs of MAPK3, MAPK8, PPARG, PTEN in the diagnosis of sepsis were 0.751, 0.611, 0.781, 0.618, and 0.857, respectively." (PMID 40070882, 2025). "Previous studies demonstrated that a specific inhibition of AGER, MAPK1, MAPK3, and RAF1 signaling reduced the expression of inflammatory cytokines and had beneficial effects during lethal sepsis." (PMID 34948374, 2021). "Additionally, THCQ has been found to regulate critical target genes in sepsis patients (such as MAPK14, MAPK3, MMP9, STAT3, and LYN), which play key roles in cellular inflammatory responses, especially through the modulation of the MAPK and Nrf2 pathways." (PMID 40963685, 2025). "Therefore, the roles of MAPK3 and MAPK8 in regulating ferroptosis, sepsis inflammatory injury mechanisms, and immune responses warrant further exploration." (PMID 40070882, 2025).
Stroke (49 papers, 2010 to 2025). Sudden impairment of blood flow to a part of the brain due to occlusion or rupture of an artery to the brain. "Based on the 95 crossover genes identified, PPI network analysis uncovered six core genes including MMP9, MAPK3, PTGS2, JUN, IL1B and TNF likely linking the activity of luteolin to effective stroke control." (PMID 34898370, 2021).
COVID-19 (41 papers, 2020 to 2025). A disease caused by infection with severe acute respiratory syndrome coronavirus 2. "MAPK3 showed significant enrichment in the Rap1 signaling pathway, the regulation of actin cytoskeleton, influenza A, and COVID-19 pathways." (PMID 40872527, 2025). "This research also showed that, out of thirteen targets, the top six (IL-6, PPARG, MAPK3, PTGS2, ICAM1, and MAPK1) are likely to be implicated in the anti-COVID-19 effects of Kochiae Fructus’ active phytomolecules." (PMID 35992697, 2022). "Similar to LHQW, these chemical compounds involved a variety of biological processes and pathways to treat COVID-19 by combining with key target proteins IL-6, ALB, and MAPK3, which supported the clinical application with COVID-19." (PMID 32483409, 2020). "Their effects in COVID-19 patients could be part of hyperinflammation for MAPK3, whereas IGF1 and EGF signaling if overactivated it can lead to fibrosis." (PMID 41227320, 2025). "The PPI network analysis exhibits that numerous genes, including IL-6, TNF-α, MAPK3, MAPK1, AKT1, mTOR, HIF1A, HSP90AA1, EGFR, CASP3, etc., are implicated in the pathogenicity of COVID-19 disease and also in the anti-COVID-19 effects of Meliae cortex’s key active phytonutrients." (PMID 36817449, 2023). "The underlying mechanisms of kaempferol against COVID-19/PF co-occurrence may be related to bind to EGFR, SRC, MAPK3, MAPK1, MAPK8, AKT1, RELA and PIK3CA." (PMID 35754492, 2022). "The top 10 of 41 potential anti-COVID-19 core targets (AKT1, TNF, HSP90AA1, IL-6, mTOR, EGFR, CASP3, HIF1A, MAPK3, and MAPK1) were identified as molecular targets of key active phytonutrients of the Meliae cortex that might be implicated in ameliorating COVID-19." (PMID 36817449, 2023). "The top three Meliae cortex’s key active phytonutrients were further analyzed for molecular docking with the top ten anti-COVID-19 core targets, including AKT1, TNF, HSP90AA1, IL-6, mTOR, EGFR, CASP3, HIF1A, MAPK3, and MAPK1." (PMID 36817449, 2023). "On the other hand, eight out of ten anti-COVID-19 core targets (TNF, EGFR, CASP3, AKT1, MAPK1, MAPK3, mTOR, and IL-6) followed the human cytomegalovirus infection." (PMID 36817449, 2023). "Nine of ten anti-COVID-19 core targets (HIF1A, EGFR, CASP3, AKT1, MAPK1, MAPK3, HSP90AA1, mTOR, and IL-6) followed the pathways in cancer." (PMID 36817449, 2023). "The top ten anti-COVID-19 core targets, AKT1, TNF, HSP90AA1, IL-6, mTOR, EGFR, CASP3, HIF1A, MAPK3, and MAPK1, were chosen for molecular docking studies with the Meliae cortex’s key active phytonutrients determined in section 3.7." (PMID 36817449, 2023). "The PPI network analysis reveals that multiple targets, including IL-6, PPARG, MAPK3, PTGS2, ICAM1, MAPK1, etc., are involved in the anti-COVID-19 effects of Kochiae Fructus’ active phytomolecules." (PMID 35992697, 2022). "According to the results of cytoscape, the targets of JFBDS for treating COVID-19 mainly contained EGFR, PIK3CA, lymphocyte-specific protein tyrosine kinase (LCK), mitogen-activated protein kinase 1 (MAPK1), MAPK3, MAPK8, STAT3, TNF, IL2 and RELA." (PMID 35165507, 2022). "The top six anti-COVID-19 core targets, IL-6, PPARG, MAPK3, PTGS2, ICAM1, and MAPK1, were molecularly docked with the three key active phytomolecules of Kochiae Fructus." (PMID 35992697, 2022). "TNF, GAPDH, MAPK3, MAPK1, EGFR, CASP3, MAPK8, mTOR, IL-2, and MAPK14 are important targets for YQS in COVID-19 treatment." (PMID 35340244, 2022).
COVID-19 (continued). "Molecular docking studies further supported these findings by identifying potential anti-UCEC/COVID-19 pharmacological biotargets of PLB, such as mitogen-activated protein kinase 3 (MAPK3), urokinase-type plasminogen activator (PLAU), and tumour necrosis factor (TNF)." (PMID 39275349, 2024). "In addition, cluster 1 confirms the existence of the top ten potential anti-COVID-19 core targets (AKT1, TNF, HSP90AA1, IL-6, mTOR, EGFR, CASP3, HIF1A, MAPK3, and MAPK1); consequently, the results of the PPI and cluster network analyses are congruent." (PMID 36817449, 2023). "Targeting TNF-α, IL-6, MAPK1, and MAPK3 might be potential alternative treatments for CRS and COVID-19." (PMID 36817449, 2023). "Previous studies on COVID-19 have suggested that FPR1 and MAPK3 may be potential therapeutic drug targets." (PMID 36052061, 2022). "Finally, IL-6, MAPK3, MAPK1, MAPK14, MAPK8, IL-1β, CCL2, EGFR, PPARG, and NOS2 were declared key targets of XFBD for COVID-19." (PMID 35185537, 2021). "Therefore, amygdalin is a candidate compound for COVID-19 treatment by regulating IL6, SRC, MAPK1, MAPK3, VEGFA and EGFR." (PMID 34908920, 2021). "Following molecular docking analysis, in silico investigation helped identify the anti-UCEC/COVID-19 pharmacological bio targets of PLB, including mitogen-activated protein kinase 3 (MAPK3), tumor necrosis factor (TNF), and urokinase-type plasminogen activator (PLAU)." (PMID 34712201, 2021). "Besides the role in supporting viral replication, MAPK3 hyperactivation can trigger inflammation (e.g., IL-6, TNF-α) and lung epithelial damage, central to severe COVID-19, and today, MAPK pathway inhibitors are under investigation to mitigate inflammation and viral replication." (PMID 41227320, 2025). "Consequently, targeting IL6, MAPK1, and MAPK3 may be a viable alternative therapeutic approach for treating CRS and COVID-19." (PMID 35992697, 2022). "Based on the biological molecular docking method, the anti-COVID-19/UCEC effect of PLB could be achieved by some of the core genes, including MAPK3, TNF, and PLAU, as PLB exerted better active cavities and binding affinity in MAPK3, TNF, and PLAU when docking." (PMID 34712201, 2021).